LGR4 (leucine rich repeat containing G protein-coupled receptor 4)
Diseases named in the same sentence as LGR4 in open-access papers (continued):
Sharing a sentence is not in itself a finding about the gene and the disease.
endometriosis (1 paper, 2021). The growth of functional endometrial tissue in anatomic sites outside the uterine body. "Here, our study demonstrated that miR-34a is a conserved repressor of LGR4 and is involved in the pathogenesis of endometriosis by inducing the release of inflammatory factors through the LGR4-NF-κB axis." (PMID 34504639, 2021).
glaucoma (1 paper, 2013). Increased pressure in the eyeball due to obstruction of the outflow of aqueous humor. "In summary, there is strong evidence that Lgr4 is a key regulator of Pitx2 in anterior segment formation and that disruption of this signaling network can result in early-onset glaucoma in a mouse model." (PMID 23840940, 2013). "Recently published work identifies Lgr4 as a receptor for Norrin, a secreted protein with established roles in retinal neuron protection and retinal vascularization and therefore suggests an additional mechanism by which Lgr4 functions to prevent glaucoma." (PMID 23840940, 2013). "Lgr4−/− retinas had detectable loss of inner nuclear layer ganglion cells and disruption of the outer nuclear layer beginning at 6 months of age in 42% of mice examined (10 of 24), strongly implicating ASD resulting from Lgr4 loss in early-onset glaucoma." (PMID 23840940, 2013). "Finally, several unanswered questions impeding a full understanding of Lgr4 in glaucoma are considered as avenues for further research." (PMID 23840940, 2013).
glioblastoma (1 paper, 2021). The most malignant astrocytic tumor (WHO grade IV). "The GB mRNA expression profiles exhibited the largest variability, although the majority of them were found to be of a Mesenchymal glioblastoma subtype assigned to the LGr4 RNA cluster." (PMID 34131149, 2021).
Graves disease (1 paper, 2017). Graves' disease is an autoimmune disorder that leads to overactivity of the thyroid gland (hyperthyroidism).It is caused by an abnormal immune system response that causes the thyroid gland to produce too much thyroid hormones. "LGR4, which is expressed in the CNS, particularly in the spinal cord, and also in other sites throughout the body, notably the skin and gastrointestinal tract, is a homolog of TSHR, the target of autoantibodies in Graves’ disease." (PMID 28533776, 2017).
Hepatic steatosis (1 paper, 2024). Steatosis is a term used to denote lipid accumulation within hepatocytes. "Mice with intestinal epithelial knockout of Lgr4 were resistant to HFD-induced adiposity, liver steatosis and deterioration of glucose tolerance." (PMID 38782937, 2024).
hyperthyroidism (1 paper, 2017). Overactivity of the thyroid gland resulting in overproduction of thyroid hormone and increased metabolic rate. "Labeling of LGR4-transduced cells occurred in 1 of the 4 NMOSD + AITD patients (patient with hyperthyroidism), and in 10 of 30 patients with MS + AITD." (PMID 28533776, 2017).
hypoaldosteronism (1 paper, 2023). "In conclusion, we describe the first patients to our knowledge harboring biallelic LGR4 variants and offer a mechanistic explanation for their life-threatening salt loss at birth, due to primary adrenal hypoaldosteronism." (PMID 36538378, 2023). "Altogether, these data show that Lgr4 inactivation is sufficient to significantly reduce WNT signaling in the adrenal cortex, which results in early-onset primary hypoaldosteronism." (PMID 36538378, 2023).
hypogonadotropic hypogonadism (1 paper, 2020). Abnormal ovarian or testicular function due to insufficient hormonal stimulation from the hypothalamic-pituitary axis. "Mutations in LGR4 have not been identified in patients with conditions of GnRH deficiency such as hypogonadotropic hypogonadism." (PMID 32493844, 2020).
imbalance (1 paper, 2023). "Heterozygous human LGR4 variants are associated with low bone mineral density, electrolyte imbalance, reduced testosterone production, and increased risk of cancers of the biliary system and skin." (PMID 36538378, 2023).
insulinoma (1 paper, 2025). "We thus first examined the effect of LGR4 signaling on the proliferation of β cells, using the rat insulinoma cell line, INS‐1 cell line." (PMID 40810739, 2025).
intestinal tumours (1 paper, 2019). "Comparing the LGR4 expression in the primary carcinomas, a greater positivity is observed in the intestinal tumours (22/37=59%) than in diffuse type (05/38=13%; P<0.0001)." (PMID 30803215, 2019).
lymph node metastasis (1 paper, 2017). "Moreover, high GPR48/LGR4 expression was an independent risk factor for lymph node metastasis (P=0.027) and the BRAFV600E mutation (P=0.009)." (PMID 29383135, 2017).
mastitis (1 paper, 2020). Inflammation of breast tissue during lactation or postpartum due to an obstructed duct or infection. "Real-time PCR results revealed that the LGR4-reference and LGR4-TV transcripts were expressed in blood neutrophils of healthy and mastitis cows." (PMID 32000686, 2020).
metastasis (1 paper, 2017). The spread or migration of cancer cells from one part of the body (where they first appeared) to another. "Elevated GPR48/LGR4 expression was significantly associated with tumor size (P=0.049), lymph node metastasis (P=0.004), recurrence (P=0.037), and the BRAFV600E mutation (P=0.003)." (PMID 29383135, 2017).
neuroblastoma (1 paper, 2023). Neuroblastoma (NB) is the most common solid, extracranial childhood tumor. "The neuroblastoma cell line SK-NA-S only expresses LGR5 as shown by us and others, and RNA-seq data showed no or little expression of LGR4, LGR6, RNF43, or ZNRF320,35." (PMID 37402772, 2023).
neuroendocrine tumors (1 paper, 2023). "If true, this suggests that neuroendocrine tumors that produce one or more RSPOs and Lgr4/5/6 would not downregulate Sstr2 expression, even if they are expressing significant levels of Wnt ligands." (PMID 36965619, 2023).
non-small cell lung carcinoma (1 paper, 2021). A group of at least three distinct histological types of lung cancer, including non-small cell squamous cell carcinoma, adenocarcinoma, and large cell carcinoma. "In non-small-cell lung carcinoma, mir-449b targets LGR4 and thus prevents cell proliferation and invasion." (PMID 33946652, 2021).
papillary thyroid carcinomas (1 paper, 2017). "The aim of this study was to investigate the role of R-spondin-GPR48/LGR4 signaling in papillary thyroid carcinomas." (PMID 29383135, 2017). "Our findings suggest that GPR48/LGR4 represents a novel target for treating differentiated thyroid carcinoma by modulating the β-catenin pathway." (PMID 29383135, 2017). "Based on this premise, we investigated the RSPO–GPR48/LGR4 signaling axis in normal thyroid gland and papillary thyroid carcinomas (PTCs)." (PMID 29383135, 2017).
Parkinson disease (1 paper, 2025). A progressive degenerative disorder of the central nervous system characterized by loss of dopamine producing neurons in the substantia nigra and the presence of Lewy bodies in the substantia nigra and locus coeruleus. "In our study, we found two patients with a clinical diagnosis of Parkinson’s disease with the genetic variant c.1087G>T (p.Gly363Cys) of the LGR4 gene." (PMID 40144372, 2025). "Thiscorrelation, together with the involvement of the LGR4protein in the WNT/β-catenin signalling pathway, leads us to speculate that the genetic variant LGR4:c.1087G>Tmay cause dysfunction or death of dopaminergic neurons,possibly leading to Parkinson’s disease." (PMID 40144372, 2025).
skin cancer (1 paper, 2018). "Nevertheless, mutations inactivating LGR4 were associated with an increased incidence of biliary tract, gallbladder and skin cancer, suggesting a tumour suppressor role of LGR4." (PMID 29316729, 2018).
thyroid (1 paper, 2017). "To date, however, few studies have investigated the function of RSPOs and GPR48/LGR4 in thyroid tumorigenesis." (PMID 29383135, 2017). "The GPR48/LGR4 mRNA is also present in normal human thyroid tissue, as revealed by Northern blot analysis, but relatively few studies have investigated the role of GPR48/LGR4 in human thyroid diseases." (PMID 29383135, 2017). "In summary, we showed that the RSPO2 and GPR48/LGR4 function in thyroid tumorigenesis, particularly in patients with regional tumor progression including LN metastasis." (PMID 29383135, 2017).
cancer (43 papers, 2012 to 2026). A tumor composed of atypical neoplastic, often pleomorphic cells that invade other tissues. "Leucine-rich repeat-containing G protein-coupled receptor 4 (LGR4) is significantly expressed in numerous cancer types and is linked to a worse patient prognosis." (PMID 38001428, 2023). "LGR4 has also been associated with cancer progression, cell migration, and invasion, mainly through the activation of the Wnt/β-catenin signaling pathway." (PMID 33946652, 2021). "Accumulating evidence indicates that LGR4 is upregulated in cancer tissues and is associated with the initiation, progression, and metastasis of a variety of cancers." (PMID 33946652, 2021). "In addition, another in vitro and experimental study reported that LGR4 was associated with a poor prognosis because its reduction decreased the number of cancer stem cells and of cells in epithelial-mesenchymal transition." (PMID 30803215, 2019). "LGR4–6 are all known to be associated with various types of cancer, but their roles and mechanisms in oncogenesis remain largely unknown." (PMID 22615920, 2012). "RSPO4 drug-conjugates targeting LGR4/5/6 simultaneously generated robust anti-tumor effect 23, 24, implying its tumor suppressive roles in human cancers." (PMID 41522353, 2026). "Our results showed that ALDH1, CD44, Sox2, Olig2, BMI1, LGR4, LGR5, Integrin α6, L1CAM, and ABC transporter associated with cancer stem cells were significantly downregulated." (PMID 39721005, 2025). "To confirm the binding profile difference of monovalent and bivalent RSPO2 furin domain forms, we examined the binding of the two forms on cancer cell lines that express either LGR4 or LGR5 endogenously." (PMID 37402772, 2023). "Consistent with this, knocking down DKK1 inhibited the ability of LGR4-overexpressing cancer cells to attract OPs." (PMID 34847079, 2022). "Corresponding to this, knockdown of LGR4 specifically in breast cells led to reduced tumor growth and invasiveness in vitro and in vivo, together with a decrease in the number of functional cancer stem cells." (PMID 35707461, 2022). "The binding of leucine-rich repeat-containing G-protein-coupled receptor 4 (LGR4) to its receptor R-spondin was reported to promote the proliferation and metastasis of cancer cells." (PMID 36091041, 2022). "Our data showed that overexpression of DKK1 in LGR4-silenced cancer cells successfully rescued the reduced OP recruitment." (PMID 34847079, 2022). "LGR4, 5, and 6, are critical regulators of embryonic development, and also have been shown to contribute to several cancers." (PMID 35707461, 2022). "There is also strong evidence that LGR4 is a key regulator of the cancer stem cell population in different types of cancer." (PMID 33946652, 2021). "Accumulating evidence indicates that LGR4 expression is upregulated in cancer tissues and participates in the regulation of various tumorigenic processes." (PMID 33946652, 2021). "It has been reported that microRNAs can regulate LGR4 expression during cancer development and progression." (PMID 33946652, 2021). "Although the LRR-containing GPCR family member Lgr5/Gpr49 is reportedly responsible for the maintenance of intestinal stem cells and cancer stem cells, the biological function of Lgr4/Gpr48 is not yet fully understood." (PMID 32943626, 2020). "In recent studies, LGR4 has been shown to promote the proliferation of cancer cells through the activation of the Wnt/β-catenin signalling pathway that plays important roles in stem cell biology, tissue homeostasis and cancer." (PMID 30803215, 2019). "GPR48/LGR4 activates the β-catenin signaling pathway and increases expression of its downstream target genes in human cancers." (PMID 29383135, 2017). "Elevated GPR48/LGR4 expression in cancer tissue is significantly correlated with regional metastasis, and upregulation of GPR48/LGR4 promotes cell proliferation in multiple cancers by stimulating Wnt/β-catenin signaling." (PMID 29383135, 2017).
cancer (continued). "To evaluate the effects of GPR48/LGR4 on cancer tumorigenesis, we transfected cells with small interfering RNA oligos (siRNA) targeting GPR48/LGR4 or with scrambled siRNA." (PMID 29383135, 2017). "This dual-mechanism model provides an explanation for the pleiotropic functions of Rspo–LGR4 signaling in normal and cancer development, particularly for the crucial role of LGR4 in tubule elongation and branching in multiple organs." (PMID 26379625, 2015). "WNT5A and LGR4 regulate cell polarity, proliferation, survival and aberrant regulation often leads to pathological conditions including cancer." (PMID 26474308, 2015). "Of the three receptors, LGR4 is the most commonly and abundantly expressed receptor in the cancer cell lines, with the exception of the HCT116 cells." (PMID 22615920, 2012). "Moreover, re-expression of LGR4 in the same cancer cells (MDA231 and BT549) restored OP recruitment." (PMID 34847079, 2022). "When overactivated later in life, LGR4 can contribute to cancer." (PMID 35707461, 2022). "LGR4 is a key molecule that can regulate both normal and cancer stem cells." (PMID 33946652, 2021). "Interestingly, LGR4 maintained cancer stem cell features and promoted tumor growth and metastasis through ELF3, an epithelium-specific transcription factor." (PMID 33946652, 2021). "Furthermore, recent evidence reveals that LGR4 is essential for the regulation of the cancer stem cell population by controlling self-renewal and regulating stem cell properties." (PMID 33946652, 2021). "RSPOs can activate three of the eight members of the LGR’s family (LGR4/5/6) and can induce a potent and sustained activation of the Wnt pathway, a well-known signaling cascade involved in several physiological and pathological processes including cancer." (PMID 33946652, 2021). "In cancer, LGR4 participates in tumor progression, invasion, and metastasis." (PMID 33946652, 2021). "In addition, other (cancer) ‘stemness’ genes (like LGR4, SOX9, KLF5 and MET) are also upregulated in the pSP." (PMID 24069258, 2013). "Therefore, LGR4-ECD protein could be a promising target for bone metastasis because of its dual function on both cancer cells and osteoclasts." (PMID 34847079, 2022). "Thus, neutralizing LGR4 activity with LGR4-ECD may have clinical utility in cancer therapy, particularly in the context of new strategies based on checkpoints inhibitors." (PMID 35707461, 2022). "LGR4 could activate the wnt/β-catenin pathway in many cancers." (PMID 36385965, 2022). "LGR4, a member of this family of receptors, participates in cell signalling, activating transcription factors related to tumour formation, potentiating the Wnt signalling pathway and playing an important role in the development of multiple organs and cancer progression." (PMID 30803215, 2019). "In addition, we detected some other ‘cancer stemness’ markers (e.g. LGR4, SOX9, KLF5, MET) as well as pancreatic embryogenesis-related factors which may be re-initiated in CSC (e.g. HNF4A)." (PMID 24069258, 2013). "By sphere formation assay, we found that FUm1/2 mutant expression lost the inhibitory effect of RSPO4 on cancer cell stemness of both LGR4+/LGR5- and LGR4-/LGR5+ tumor cells." (PMID 41522353, 2026). "Next, we analyzed RNA-seq data of 24 NB cell lines in the Cancer Cell Line Encyclopedia (CCLE) database and found that LGR5 expression was relatively high in about half of the cell lines whereas LGR4 was expressed at lower levels in nearly all the cell lines." (PMID 39065640, 2024). "In the premetastatic niche in vivo model, overexpression of DKK1 in human SCP46 cancer cells restored the serum level of human DKK1 protein inhibited by LGR4 knockdown and reversed the effects of LGR4 silencing on OP number and osteoclast number and activity." (PMID 34847079, 2022). "LGR4-ECD mediates its therapeutic effects differentially in different tissues, through binding RSPOs in cancer cells, and binding RANKL in osteoclasts." (PMID 35707461, 2022).
cancer (continued). "Group B includes LGR4, LGR5, and LGR6 receptors, which play crucial roles in developmental processes and are involved in several types of cancer." (PMID 33946652, 2021). "Hence, this paper provided an overview of the molecular characteristics and signaling mechanisms of LGR4, its involvement in multiple organ development and participation in the modulation of immunology related diseases, metabolic diseases, and oxidative stress damage along with cancer progression." (PMID 35140734, 2021). "We also identified 5 genes (LGR4, RARG, PNISR, PCOLCE2, RALGDS) that shared the same patterns across three types of cancer, and 39 genes with two overlaps across eight cancer types." (PMID 32764426, 2020). "Similar to the controversial roles of LGR6 in different types of cancer, LGR proteins, including LGR4–6, have been demonstrated to play an opposite, even paradoxical, role in regulating Wnt/β-catenin signaling." (PMID 31193124, 2019). "We also investigated the RSPO2–GPR48/LGR4 signaling axis in Nthy-ori3-1 cells, which express lower endogenous levels of RSPO2 than cancer cells." (PMID 29383135, 2017). "Thus, LGR4/5 and ZNRF3 are required for RSPO4-induced suppression of Wnt/β-catenin signaling in cancer cells." (PMID 41522353, 2026). "Moreover, knockdown of LGR4 in A2780 and OVCAR3 cells largely antagonized the growth promotive effect of RSPO2 and partially impaired the RSPO2-induced cancer cell migration." (PMID 36217544, 2022). "The role of LGR4 signaling through its newly discovered ligand (RANKL) in the homeostasis of most tissues and their implication in cancer is still unknown." (PMID 33946652, 2021). "Although the involvement of the LRG4–RANKL axis in cancer has not yet been clearly determined, LGR4 nevertheless promotes the proliferation of various tumour cells, including breast, prostate, gastric and hepatic cancer." (PMID 27279652, 2016). "Finally, we identified cell surface markers for cardiac progenitors, such as the Leucine-rich repeat-containing G-protein coupled receptor 4 (LGR4), belonging to the same subfamily of LGR5, and LGR6, established tissue/cancer stem cells markers." (PMID 26783251, 2016). "Additionally, LGR4 is expressed preferentially in the cancer stem cell subset compared to non-cancer stem cells." (PMID 33946652, 2021). "Our data showed that knockdown of LGR4, but not RANK, in cancer cells dramatically decreased the RANKL-induced recruitment of primary cultured OPs." (PMID 34847079, 2022).